CYP27C1 (cytochrome P450 family 27 subfamily C member 1)
Description:
[Isoform 2]: A cytochrome P450 monooxygenase that catalyzes the 3,4 desaturation of all-trans-retinol (also called vitamin A1) to all-trans-3,4-didehydroretinol (also called vitamin A2) in the skin. Desaturates with lower efficiency all-trans retinal and all-trans retinoic acid. Forms minor amounts of 3-hydroxy and 4-hydroxy all-trans-retinol derivatives. Mechanistically, uses molecular oxygen inserting one oxygen atom into a substrate and reducing the second into a water molecule. Two electrons are provided by NADPH via a two-protein mitochondrial transfer system comprising flavoprotein FDXR (adrenodoxin/ferredoxin reductase) and nonheme iron-sulfur protein FDX1 or FDX2 (adrenodoxin/ferredoxin).
Synonyms: FLJ16008
Tractability: Antibody: UniProt places it where antibodies can reach, with medium confidence. PROTAC: ubiquitination databases record sites on it.
Gene: Protein-coding gene on chromosome 2 (127,183,832 to 127,220,385, reverse strand). Ensembl gene ENSG00000186684.
Subcellular location: Mitochondrion membrane (Isoform 2)
Subcellular location (Human Protein Atlas): Vesicles
Gene Ontology:
Molecular function: 11-cis retinal binding; 11-cis-retinal 3,4-desaturase activity; all-trans retinal 3,4-desaturase activity; all-trans retinal binding; all-trans retinoic acid 3,4-desaturase activity; all-trans retinol 3,4-desaturase activity; all-trans-retinol binding; retinoic acid binding; heme binding; iron ion binding; monooxygenase activity; oxidoreductase activity, acting on paired donors, with incorporation or reduction of molecular oxygen
Biological process: retinal metabolic process; retinoic acid metabolic process; retinol metabolic process; lipid metabolic process
Cellular component: mitochondrion; mitochondrial membrane
Genetic constraint (gnomAD): Loss-of-function variants: 31 observed, 44.06 expected, observed/expected ratio (o/e) 0.7, 90% interval 0.53 to 0.95. The upper end of that interval is the gene's LOEUF score, 0.95, which puts it in group 4 of 6, group 1 being the genes least tolerant of losing a copy. Missense variants: 390 observed, 509.05 expected, observed/expected ratio (o/e) 0.77, 90% interval 0.7 to 0.83. Synonymous variants: 198 observed, 198.1 expected, observed/expected ratio (o/e) 1, 90% interval 0.89 to 1.12.
Homologues: Orthologues: dog CYP27C1 (87% identical), rabbit CYP27C1 (77% identical), macaque CYP27C1 (69% identical), zebrafish cyp27c1 (64% identical), Drosophila melanogaster sad (23% identical). Paralogues in human: CYP27B1 (37% identical), CYP27A1 (35% identical), CYP24A1 (30% identical).
Diseases named in the same sentence as CYP27C1 in open-access papers:
CYP27C1 is named in the same sentence as 6 diseases in open-access papers, as found by Europe PMC text mining. Sharing a sentence is not in itself a finding about the gene and the disease. The quoted sentences say what the papers report.
Alzheimer disease (1 paper, 2019). A progressive, neurodegenerative disease characterized by loss of function and death of nerve cells in several areas of the brain leading to loss of cognitive function such as memory and language. "We found that CHRM1 (having putative G4/iMs in first 500 bp upstream), CYP27C1 and FOXH1 (having putative G4/iMs in their first 200 bp upstream) are all linked to pathways related to Alzheimer’s disease." (PMID 31597270, 2019).
lung carcinoma (1 paper, 2022). "Strikingly, all the inhibitors partially lost their cytotoxicity in stable CYP27C1-knockdown human lung cancer cells." (PMID 35887201, 2022). "Here, to further explore the biological functions of CYP27C1 in human lung cancer cells, and evaluate the possibility of that being a target gene for lung cancer treatment, we established stable CYP27C1-knockdown human lung cancer cell lines." (PMID 35887201, 2022). "To further study the functions of CYP27C1 in human lung cancer, we first established stable CYP27C1-knockdown A549 and H1975 cell lines, and stable CYP27C1-overexpressed H460 cell line." (PMID 35887201, 2022). "Here, we study the functions of CYP27C1 in lung cancer progression and drug endurance, and explore its potential to be a diagnostic and therapeutic target for lung cancer management." (PMID 35887201, 2022). "In this study, we found that CYP27C1 was differentially expressed in human lung cancer cell lines compared to human normal bronchial epithelial BEAS-2B cells." (PMID 35887201, 2022). "Preliminary data shows differential expression levels of CYP27C1, one of the “orphan P450s” in human lung cancer cell lines." (PMID 35887201, 2022). "The potency of vinorelbine and protein kinase inhibitors was aggressively impaired by CYP27C1-knockdown, and revealed that CYP27C1 was critical for vinorelbine or protein kinase inhibitors inducing cytotoxicity in human lung cancer cells." (PMID 35887201, 2022). "In this study, we found that modulation of the expression of CYP27C1 in human lung cancer cell lines affects their sensitivity towards vinorelbine, which is a front-line anticancer drug." (PMID 35887201, 2022). "Despite lack of evidence showing direct connection between the expression level of CYP27C1 and lung cancer, links between other CYP450 family members and carcinogenesis have been reported." (PMID 35887201, 2022). "Quantitative real-time PCR and immunoblot assays were conducted to estimate the transcription and protein expression level of CYP27C1 in human lung cancer cell lines, which was relatively higher in A549 and H1975 cells, but was lower in H460 cells." (PMID 35887201, 2022). "Accidently, we found a disparity of expression levels of CYP27C1 in different human lung cancer cell lines, implicating that CYP27C1 is probably involved in lung cancer development." (PMID 35887201, 2022). "Furthermore, the discrepancy of IC50 values of several anticancer agents in different human lung cancer cell lines aroused our interests in the relationship between CYP27C1 expression levels and anticancer drug sensitivity in human lung cancer." (PMID 35887201, 2022). "Therefore, CYP27C1 plays an indispensable role in dictating the cellular sensitivity of human lung cancer cells towards anticancer agents." (PMID 35887201, 2022). "Analysis of the expression level of CYP27C1 in different human lung cancer cell lines showed that the mRNA level of CYP27C1 was significantly higher in A549 (p = 0.0276) and H1975 (p = 0.0007), and relatively lower in H460 (p = 0.0014), compared to that in BEAS-2B cells." (PMID 35887201, 2022). "Here, we intended to investigate whether there are latent connections between the expression level of CYP27C1 and lung cancer development." (PMID 35887201, 2022). "To further explore the relationship between CYP27C1 expression level and potency of protein kinase inhibitors, as well as their resistance in human lung cancer cells, we employed stable CYP27C1-knockdown A549, H1975 cells, and detected cell viability with the treatment of each inhibitor." (PMID 35887201, 2022).
lung carcinoma (continued). "Therefore, uplifting the expression level or the catalytic activity of CYP27C1 might benefit lung cancer management." (PMID 35887201, 2022). "Therefore, the possibility of vinorelbine being a novel substrate of CYP27C1, and the mechanism interpreting why CYP27C1 has impact on sensitivity of human lung cancer cells towards vinorelbine, could be our focus in further studies." (PMID 35887201, 2022). "To further investigate whether the expression level of CYP27C1 contributes to the alteration of vinorelbine potency in human lung cancer cells, we tested the sensitivity of stable CYP27C1-knockdown cells and stable CYP27C1-overexpressed cells toward vinorelbine." (PMID 35887201, 2022). "Previously, to seek for the feasible target genes which might affect the progression and chemotherapeutic response in lung cancer, we detected the expression level of CYP450 genes in human lung cancer cell lines, and identified several differentially expressed CYP450 genes, one of which is CYP27C1." (PMID 35887201, 2022). "In addition, we found that the protein expression level of CYP27C1 was relatively higher in A549 (p = 0.0037), H1299 (p = 0.0177) and H1975 (p = 0.0431) in comparison with BEAS-2B cells, indicating that the mRNA and protein expression level of CYP27C1 is aberrant in some human lung cancer cells." (PMID 35887201, 2022).
tumor (2 papers, 2022 to 2024). "Tumor weight of stable CYP27C1-knockdown group was significantly higher than that of control group (p = 0.0357)." (PMID 35887201, 2022). "To further verify the effects of CYP27C1 in cancer growth in vivo, we implanted the stable CYP27C1-knockdown H1975 cells and control cells into BALB/c nude mice and measured the tumor volume and tumor weight." (PMID 35887201, 2022).
cancer (1 paper, 2022). A tumor composed of atypical neoplastic, often pleomorphic cells that invade other tissues. "In order to investigate whether CYP27C1 is involved in regulating cancer cell growth, we compared the proliferation rate of the stable CYP27C1-knockdown cells, stable CYP27C1-overexpressed cells, and the corresponding control cells." (PMID 35887201, 2022).
CYP27C1 also shares sentences with these, for which no sentence is quoted: lung adenosquamous carcinoma (1 paper); melanoma (1).